DOCK7 (dedicator of cytokinesis 7)
Description:
Functions as a guanine nucleotide exchange factor (GEF), which activates Rac1 and Rac3 Rho small GTPases by exchanging bound GDP for free GTP. Does not have a GEF activity for CDC42. Required for STMN1 'Ser-15' phosphorylation during axon formation and consequently for neuronal polarization. As part of the DISP complex, may regulate the association of septins with actin and thereby regulate the actin cytoskeleton. Has a role in pigmentation (By similarity). Involved in the regulation of cortical neurogenesis through the control of radial glial cells (RGCs) proliferation versus differentiation; negatively regulates the basal- to-apical interkinetic nuclear migration of RGCs by antagonizing the microtubule growth-promoting function of TACC3 (By similarity).
Synonyms: KIAA1771; ZIR2; DEE23; EIEE23
Tractability: PROTAC: ubiquitination databases record sites on it; its protein half-life has been measured.
Gene: Protein-coding gene on chromosome 1 (62,454,298 to 62,688,464, reverse strand). Ensembl gene ENSG00000116641.
Subcellular location: Cell projection, axon
Pathways (Reactome):
Signal Transduction: CDC42 GTPase cycle; MET activates RAP1 and RAC1; RAC1 GTPase cycle
Hemostasis: Factors involved in megakaryocyte development and platelet production
Gene Ontology:
Molecular function: GTPase activator activity; protein binding; small GTPase binding; guanyl-nucleotide exchange factor activity
Biological process: axonogenesis; establishment of neuroblast polarity; microtubule cytoskeleton organization; neuron projection development; positive regulation of vascular associated smooth muscle cell migration; Rac protein signal transduction; interkinetic nuclear migration; negative regulation of cold-induced thermogenesis; regulation of neurogenesis; regulation of Rho protein signal transduction; septin ring organization; small GTPase-mediated signal transduction
Cellular component: COP9 signalosome; focal adhesion; axon; basal part of cell; growth cone; neuron projection
Genetic constraint (gnomAD): Loss-of-function variants: 99 observed, 212.21 expected, observed/expected ratio (o/e) 0.47, 90% interval 0.4 to 0.55. The upper end of that interval is the gene's LOEUF score, 0.55, which puts it in group 2 of 6, group 1 being the genes least tolerant of losing a copy. Missense variants: 1,813 observed, 2,325.9 expected, observed/expected ratio (o/e) 0.78, 90% interval 0.75 to 0.81. Synonymous variants: 738 observed, 807.63 expected, observed/expected ratio (o/e) 0.91, 90% interval 0.86 to 0.97.
Gene-disease validity (ClinGen):
ClinGen rates the evidence that DOCK7 causes each of these diseases.
genetic developmental and epileptic encephalopathy (autosomal recessive): Definitive. A complex neurodevelopmental disorder characterized by a range of developmental delays and epileptic encephalopathy phenotypes.
Homologues: Orthologues: chimpanzee DOCK7 (99% identical), macaque DOCK7 (99% identical), dog DOCK7 (99% identical), pig DOCK7 (99% identical), rat Dock7 (98% identical), mouse Dock7 (98% identical), tropical clawed frog dock7 (92% identical), rabbit DOCK7 (92% identical), guinea pig DOCK7 (90% identical), zebrafish dock7 (89% identical), Drosophila melanogaster Zir (47% identical), Caenorhabditis elegans F46H5.4 (31% identical), and 1 more. Paralogues in human: DOCK6 (65% identical), DOCK8 (56% identical), DOCK11 (30% identical), DOCK9 (29% identical), DOCK10 (28% identical), DOCK2 (15% identical), DOCK5 (14% identical), DOCK1 (14% identical), DOCK3 (14% identical), DOCK4 (14% identical).
Diseases named in the same sentence as DOCK7 in open-access papers:
DOCK7 is named in the same sentence as 54 diseases in open-access papers, as found by Europe PMC text mining. Sharing a sentence is not in itself a finding about the gene and the disease. The quoted sentences say what the papers report.
Epileptic encephalopathy (7 papers, 2014 to 2026). A condition in which epileptiform abnormalities are believed to contribute to the progressive disturbance in cerebral function. "Aberrant expression of DOCK7 that codes for a guanine nucleotide exchange factor is associated with epileptic encephalopathy." (PMID 37026480, 2023). "In keeping with observations that DOCK7 is crucial for neural processes, several studies have identified pathological links between premature stop codon mutations in DOCK7 that resulted in truncated protein and epileptic encephalopathy and cortical blindness." (PMID 33684443, 2021). "Recently, mutation in DOCK7 has been found to be associated with epileptic encephalopathies, dysmorphic features and intellectual disability." (PMID 26997977, 2016). "Given that epileptic encephalopathies are a set of disorders that result in seizure activity and associated cognitive and behavioral impairments, we investigated the role of Dock7 in seizure susceptibility and flurothyl kindling using the repeated flurothyl seizure model in mice." (PMID 42079280, 2026). "Mutations in DOCK7 have been identified in individuals with epileptic encephalopathies." (PMID 42079280, 2026). "The loss of DOCK7 function in cortical interneurons may underlie the abnormal development of GABAergic networks that could lead to the seizures observed in individuals with epileptic encephalopathies that carry truncating mutations in the gene for DOCK7." (PMID 25309333, 2014). "A splice site variant identified in DOCK7 (c.5724 + 1G > T), in a patient with seizures and severe ILD associated with microcephaly, was a novel disease gene at time of sequencing our patient, but was subsequently reported in patients with developmental and epileptic encephalopathy." (PMID 37946251, 2023).
glioblastoma (6 papers, 2017 to 2023). The most malignant astrocytic tumor (WHO grade IV). "HGF stimulation of glioblastoma resulted in interactions of Dock7 and c-Met in a manner that is dependent on the adaptor protein Gab1, which also interacts with Dock7 in an HGF-dependent manner." (PMID 28475121, 2017). "A role for DOCK7 in migration has been described in neuroblasts, Schwann cells and U-87MG glioblastoma cells 119-121, but DOCK7 has not been previously linked to entosis." (PMID 37064875, 2023). "Also, GAB1 has been reported to be closely involved in glioblastoma cell invasion through HGF-induced activation of dedicator of cytokinesis 7 (DOCK7) and RAC1." (PMID 37627207, 2023). "DOCK7 is a RAC-GEF with the potential to regulate F-actin organization, consistent with previous publications reporting DOCK7-mediated RAC1/CDC42 - PAK1 activation in the DNA replication stress response 122, and the promotion of glioblastoma cell invasion by DOCK7 via RAC activation." (PMID 37064875, 2023). "DOCK7-controlled migration can also be pathological; it was identified to be required for human hepatocyte growth factor (HGF)-induced glioblastoma tumor cell invasion, with upregulated DOCK7 found in astrocytoma human glioblastoma compared with nonneoplastic brain." (PMID 33684443, 2021).
Obesity (4 papers, 2016 to 2021). Accumulation of substantial excess body fat. "Our key findings were the robust POE of variants at the LPL and DOCK7/ANGPTL3 loci on obesity measures in both family cohorts, and the same variants also showed POE on lipid traits in the Botnia family study." (PMID 35052431, 2021). "DOCK7, which presented associations with the 46 traits (p-value ≤ 4.42 × 10−57), HsCRP (p-value ≤ 3.66 × 10−53) and BMI (p-value ≤ 9.36 × 10−7), has been associated with heart disease and ischemic stroke and overweight and obesity." (PMID 29040274, 2017). "Sex-specific parental effects were also observed; variants at ANGPTL3/DOCK7 showed POE on lipid traits and obesity in daughters only, while those at LPL and TMEM57 showed POE on lipid traits in sons." (PMID 35052431, 2021). "Variants at LPL and DOCK7/ANGPTL3 showed POE on obesity-related traits in Botnia and HTB, and POE effects on obesity were seen to a higher degree in daughters." (PMID 35052431, 2021).
developmental and epileptic encephalopathy 23 (3 papers, 2021 to 2022). "Dedicator of cytokinesis protein 7 (DOCK7), which is localized to the developing axons, activates Rac1 and Rac3 small GTPases and regulates neuronal polarity; moreover, its variants cause developmental and epileptic encephalopathy 23 (DEE23)." (PMID 36030824, 2022).
breast carcinoma (2 papers, 2021 to 2024). "Interestingly, the expression of DHR1L in Dock7 knockdown MDA-MB-231 breast cancer cells helped the cells to survive the initial implantation and form tumors, while cells expressing DHR1-C2M were less effective at forming tumors." (PMID 36711811, 2024). "Searching the Cancer Genome Atlas (TCGA) Breast Cancer Dataset (BRCA), we found that unlike other members of the Dock-C subfamily of Dock180 proteins, Dock7 is highly upregulated in triple-negative breast cancer patients." (PMID 36711811, 2024).
coronary artery atherosclerosis (2 papers, 2018 to 2021). "The DOCK7-ANGPTL3 SNPs and their haplotypes were associated with the angiographic severity to coronary artery atherosclerosis and the risk of CAD and IS in the Southern Chinese Han population." (PMID 35047576, 2021). "This study showed that the DOCK7 rs1748195 SNP and rs1748195G-rs12563308T haplotype were associated with an increased risk of CAD and the severity to coronary atherosclerosis, whereas the ANGPTL3 rs12563308 SNP was associated with a decreased risk of CAD." (PMID 29454388, 2018). "In the current study, we showed that the DOCK7 rs1748195 SNP and rs1748195G-rs12563308T haplotype were associated with an increased risk of CAD and the severity to coronary atherosclerosis, whereas the ANGPTL3 rs12563308 SNP was associated with a decreased risk of CAD." (PMID 29454388, 2018).
coronary artery disease (2 papers, 2018 to 2024). "In large-scale cross-sectional analyses, the DOCK7 variant has been identified as a genetic determinant of blood lipid levels, particularly in increasing triglyceride levels, which contributes to a higher risk of coronary artery disease." (PMID 39458547, 2024).
epilepsy (2 papers, 2021 to 2025). A brain disorder characterized by episodes of abnormally increased neuronal discharge resulting in transient episodes of sensory or motor neurological dysfunction, or psychic dysfunction. "Notably, we found eight proteins shared by stroke and epilepsy (e.g., SH3BGRL3, PTPMT1), nine shared by epilepsy and VaD (e.g., DOCK7, BCAN), and ten by stroke and VaD (e.g., MTHFR, UVRAG), suggesting common pathogenic axes like inflammation and cellular stress." (PMID 40624693, 2025).
hepatocellular carcinoma (2 papers, 2021 to 2025). A malignant tumor that arises from hepatocytes. "Moreover, O-GlcNAc of ZNF263 at Ser 662 promotes its chromatin association with OGT and facilitates its binding to the promoters of genes such as DOCK7, NPTX1, and UFSP2, thereby influencing hepatocellular carcinoma (HCC) progression." (PMID 41280891, 2025).
Intellectual disability (2 papers, 2016 to 2025). "Interestingly, DGDP005 displays some of the phenotypes expected from DOCK7 mutation indicating that DOCK7 may also contribute to intellectual disability and craniofacial anomalies in our patient." (PMID 26997977, 2016). "We also determined the transcript levels of six candidate genes (DAB1, HOOK1, NFIA, DOCK7, DNAJC6 and PDE4B) for syndromic intellectual disability." (PMID 26997977, 2016). "We propose six candidate genes (DAB1, HOOK1, DOCK7, DNAJC6, PDE4B, and NFIA) for the clinical features such as intellectual disability and OCD observed in DGDP005, because each of these genes is involved directly or indirectly in neurological disorders." (PMID 26997977, 2016). "Comparative deletion mapping showed that there are at least six candidate genes including, NFIA, HOOK1, DOCK7, DAB1, DNAJC6, and PDE4B, that could contribute to the syndromic or non-syndromic intellectual disability." (PMID 26997977, 2016).
osteosarcoma (2 papers, 2020 to 2021). A usually aggressive malignant bone-forming mesenchymal neoplasm, predominantly affecting adolescents and young adults. "Furthermore, in osteosarcoma cell lines, the SNHG4/miR-224-3p/DOCK7 axis was implicated in the regulation of cell proliferation, migration, and invasion." (PMID 33088220, 2020).
cardiac hypertrophy (1 paper, 2023). "Its downregulation has been associated with T2D progression and cardiac hypertrophy, together with an effect on its potential regulator dedicator of cytokinesis (DOCK7)." (PMID 37742032, 2023).
cervical cancer (1 paper, 2024). A primary or metastatic malignant neoplasm involving the cervix. "The knockdown of Dock7 also impacted the ability of HeLa cervical cancer cells and A549 lung cancer cells to form colonies, establishing that Dock7 is necessary for the transformed properties of multiple cancer cell types." (PMID 36711811, 2024).
Escobar syndrome (1 paper, 2021). "Escobar syndrome can also be caused by pathogenic variants in CNTN1 (contactin 1) and DOCK7 (dedicator of cytokinesis 7)." (PMID 34440395, 2021).
hyperlipidaemia (1 paper, 2016). "Assessment of the association between the DOCK7, PCSK9 and GALNT2 loci identified through GWAS 28, 29, 30 with the risk of hyperlipidaemia has become fundamental in the validation of these signals." (PMID 26493351, 2016). "Third, although we have detected the interactions of the DOCK7, PCSK9 and GALNT2 SNPs on hyperlipidaemia in this study, many unmeasured environmental and genetic factors still need to be considered." (PMID 26493351, 2016). "Although the association of some DOCK7, PCSK9 and GALNT2 SNPs and serum lipid levels has been reported in several previous studies, the association of the novel variants and their haplotypes and possible gene–gene interaction with the risk of hyperlipidaemia has never been detected previously." (PMID 26493351, 2016).
inflammatory bowel disease (1 paper, 2023). A spectrum of small and large bowel inflammatory diseases of unknown etiology. "Co-localisation analyses across genetic effects on DNA methylation and 56 human traits identify 1520 co-localisations across 1325 unique CpGs and 34 phenotypes, including in disease-relevant genes, such as USP1 and DOCK7 (total cholesterol levels), and ICOSLG (inflammatory bowel disease)." (PMID 37525248, 2023).
kidney stones (1 paper, 2024). "Notably, genes PPP2R3A for BUN, VAMP8 for UACR, DOCK7 for creatinine, and HIBADH for kidney stones were identified as shared risk genes by all three methods." (PMID 39086896, 2024).
ovarian carcinoma (1 paper, 2024). A malignant neoplasm originating from the surface ovarian epithelium. "DOCK7 has also been reported to be highly expressed in ovarian cancer, and is recruited into the nucleus by MDC1 to participate in the DNA damage response through the RAC1/CDC42/PAK1 module." (PMID 38385857, 2024). "Deletion of DOCK7 can increase the sensitivity of ovarian cancer cells to chemotherapy." (PMID 38385857, 2024). "In addition, high expression level of DOCK7 was found in ovarian cancer and tended to be a potential target for chemotherapy." (PMID 38385857, 2024).
paranoid schizophrenia (1 paper, 2017). "For example, genes involved in the neuregulin 1–ErbB4 signaling pathway, including DOCK7, EGFR, PTPRZ1 and the key regulator ERBB4,45, 46, 47 were downregulated in undifferentiated and disorganized schizophrenia, while they were upregulated in paranoid schizophrenia." (PMID 28809853, 2017).
prostate carcinoma (1 paper, 2019). A carcinoma that arises from epithelial cells of the prostate gland. "Amongst the genes containing ESRP2-repressed exons that were also skipped in response to androgen stimulation were DOCK7 (exon 23), which encodes a guanine nucleotide exchange factor involved in cell migration; and RPS24 (exon 5), a gene that is highly expressed in prostate cancer." (PMID 31478829, 2019).
prostate tumours (1 paper, 2019). "(F) Percentage splicing inclusion (PSI), quantified by RT-PCR, of DOCK7 exon 23 within samples of prostate tumour and adjacent normal tissue (statistical significance calculated using t test)." (PMID 31478829, 2019). "Further qRT-PCR analysis of an independent cohort confirmed more frequent skipping of DOCK7 (exon 23) and RPS24 (exon 5) in prostate tumour tissue compared to normal prostate." (PMID 31478829, 2019).
Sepsis (1 paper, 2024). Sepsis is defined as life-threatening organ dysfunction caused by a dysregulated host response to infection. "DOCK7 is associated with serum lipid level, which are known to play a role in both sepsis and kidney health." (PMID 39086896, 2024).
virus infections (1 paper, 2023). "Although the specific role for Dock7 in regards to virus infections has never been identified, other GEF proteins have been shown to play a role in virus infections or in the mediation of the inflammatory response." (PMID 38257770, 2023).
tumor (7 papers, 2021 to 2025). "In mice, we find that Dock7 is critical for tumor formation, suggesting Dock7 may play an important role in supporting cancer survival during the more stressful stages of tumor progression such as tumor initiation from solitary tumor cells and seeding of secondary metastatic sites." (PMID 36711811, 2024). "In contrast, patients with insufficient expression of SORBS2, PAM, ZFAT, DOCK7, ERMAP, BTF3, and GUSB in the tumor tissues had shorter survival duration than patients in the high-expression group." (PMID 37315301, 2023). "Second, DOCK7 is certainly not the only functional molecule in TAM‐EVs that can regulate tumour metastasis." (PMID 38385857, 2024).
cancer (3 papers, 2021 to 2024). A tumor composed of atypical neoplastic, often pleomorphic cells that invade other tissues. "Here, we describe a novel multiprotein complex (DockTOR) essential for the survival of cancer cells under stress, triggered by the GTPase Cdc42 and a signaling partner Dock7, which includes AKT, mTOR, and the mTOR regulators TSC1, TSC2, and Rheb." (PMID 36711811, 2024). "Murine Embryonic Fibroblasts (MEFs) derived from Dock7 KO mice did not experience a decrease in survival when grown in serum-free conditions suggesting that the ability of Dock7 to provide a survival benefit may be specific for cancer cells." (PMID 36711811, 2024). "Dock7, together with mTOR, AKT and S6K, promotes signaling activities essential for cancer cell survival." (PMID 36711811, 2024). "Both Dock7 knockdown and AKT inhibition completely prevented cancer cells from exhibiting anchorage-independent growth and survival during serum deprivation." (PMID 36711811, 2024). "DockTOR enables cancer cells to maintain a low but critical mTORC2-dependent phosphorylation of AKT during serum deprivation by preventing AKT dephosphorylation through an interaction between phospho-AKT and the Dock7 DHR1 domain." (PMID 36711811, 2024).
cardiovascular disease (1 paper, 2019). "Likewise, DOCK7 rs10889334, previously associated with total cholesterol and cardiovascular disease via linkage disequilibrium, was also associated with LDL-C and smoking phenotype classes in the same direction." (PMID 31891604, 2019).
DOCK7 also shares sentences with these, for which no sentence is quoted: autism spectrum disorder (2 papers); colorectal cancer (2); dyslipidemia (2); infantile epileptic encephalopathy (2); ischemic stroke (2); neurodevelopmental disorder (2); aortic aneurysm (1); astrocytoma (1); atherosclerosis (1); autosomal recessive disease (1); Cognitive impairment (1); colon cancer (1); cortical blindness (1); esophageal squamous cell carcinoma (1); Fanconi anemia (1); heart disease (1); hypercholesterolaemia (1); hypertriglyceridaemia (1); liposarcoma (1); lung carcinoma (1); mental disorder (1); microcephaly (1); neurological disorders (1); Seizure (1); spinocerebellar ataxia (1); Stroke (1); triple-negative breast carcinoma (1); type 2 diabetes (1).